PKHD1L1 (PKHD1 like 1)
Description:
Component of hair-cell stereocilia coat. Required for normal hearing.
Synonyms: DFNB124; PKHDL1
Tractability: Antibody: UniProt predicts a signal peptide or a membrane-spanning region; its Gene Ontology location is reachable by antibodies, with medium confidence.
Gene: Protein-coding gene on chromosome 8 (109,362,461 to 109,537,207, forward strand). Ensembl gene ENSG00000205038.
Subcellular location: Membrane; Cell projection, stereocilium membrane
Subcellular location (Human Protein Atlas): Flagellar centriole; Mid piece; Principal piece
Gene Ontology:
Molecular function: signaling receptor activity
Biological process: immune response
Cellular component: cytosol; extracellular region; membrane; stereocilium coat; stereocilium membrane; stereocilium tip
Genetic constraint (gnomAD): Loss-of-function variants: 297 observed, 310.08 expected, observed/expected ratio (o/e) 0.96, 90% interval 0.87 to 1.05. The upper end of that interval is the gene's LOEUF score, 1.05, which puts it in group 4 of 6, group 1 being the genes least tolerant of losing a copy. Missense variants: 4,103 observed, 4,131.9 expected, observed/expected ratio (o/e) 0.99, 90% interval 0.97 to 1.02. Synonymous variants: 1,443 observed, 1,456.1 expected, observed/expected ratio (o/e) 0.99, 90% interval 0.95 to 1.03.
Homologues: Orthologues: chimpanzee PKHD1L1 (99% identical), macaque PKHD1L1 (96% identical), dog PKHD1L1 (87% identical), rabbit PKHD1L1 (85% identical), pig PKHD1L1 (85% identical), guinea pig PKHD1L1 (83% identical), mouse Pkhd1l1 (82% identical), rat Pkhd1l1 (82% identical), tropical clawed frog pkhd1l1.1 (56% identical), zebrafish pkhd1l1.1 (52% identical), zebrafish pkhd1l1.2 (50% identical). Paralogues in human: PKHD1 (24% identical), DST (10% identical), MACF1 (10% identical), PLEC (9% identical), SYNE1 (8% identical), SYNE2 (7% identical), FLNC (7% identical), SPTBN2 (7% identical), FLNA (7% identical), SPTBN1 (7% identical), FLNB (7% identical), SPTBN4 (6% identical), and 24 more.
Diseases named in the same sentence as PKHD1L1 in open-access papers:
PKHD1L1 is named in the same sentence as 35 diseases in open-access papers, as found by Europe PMC text mining. Sharing a sentence is not in itself a finding about the gene and the disease. The quoted sentences say what the papers report.
cutaneous melanoma (3 papers, 2022 to 2025). A primary melanoma arising from atypical melanocytes in the skin. "We found that the PKHD1L1 mRNA expression levels were significantly lower in skin cutaneous melanoma (SKCM) and lung adenocarcinoma (LUAD) than in normal tissues." (PMID 38203530, 2023). "Among them, PKHD1L1, LRP1B, ADGRV1 and DNAH10 were hypomethylated in UV-mutant compared with non UV-mutant cutaneous melanoma patients in BCH." (PMID 35840550, 2022).
deafness (3 papers, 2022 to 2023). An inherited or acquired condition characterized by the complete loss of the ability to hear from one or both ears. "Thirty-eight genes were common to all three analyses, one of which was a known deafness gene (PKHD1L1)." (PMID 37163093, 2023). "PKHD1L1, DUOX2, CELSR1, ELMO3, ARHGAP21, LMO7 and UBE3B are all defined as deafness genes through work on the mouse orthologues." (PMID 37163093, 2023).
female infertility (3 papers, 2024 to 2025). Diminished or absent ability of a female to achieve conception. "Among the variants associated with multiple subtypes of female infertility is rs1964514, an intronic variant in PKHD1L1 (OR (95% CI) for F-ALL=1.13 (1.09–1.16), F-EXCL=1.13 (1.09–1.17), F-INCL=1.18 (1.11–1.25))." (PMID 38562841, 2024). "Among the variants associated with multiple subtypes of female infertility is rs9643050 (MAF of 6.01%), an intronic variant in PKHD1L1 (F-ALL, odds ratio (OR) (95% confidence interval (CI)) 1.13 (1.09–1.16); F-EXCL, OR 1.13 (1.09–1.17); F-INCL, OR 1.18 (1.11–1.25))." (PMID 40229599, 2025).
melanoma (3 papers, 2018 to 2023). A malignant, usually aggressive tumor composed of atypical, neoplastic melanocytes. "The results also showed that PKHD1L1 expression was positively associated with patient survival in the melanoma dataset GSE19234 (OS, hazard ratio (HR) = 0.62 (0.39–0.98), p = 0.042304) and lung cancer dataset GSE8894 (relapse-free survival (RFS), HR = 0.46 (0.22–0.94), p = 0.034149)." (PMID 38203530, 2023). "The aim of this study was to investigate the PKHD1L1 expressions in various cancers using multiomic analysis, and to confirm the clinical relevance of PKHD1L1 through the association between PKHD1L1 expression and the survival of melanoma and lung cancer patients." (PMID 38203530, 2023). "We analyzed the PKHD1L1 expression in single-cell RNA-sequencing datasets using the TISCH database to determine the cell types expressing PKHD1L1 in melanoma and NSCLC." (PMID 38203530, 2023). "A strong association between the expressions of PKHD1L1 and LAX1 was also confirmed using the Mixed Melanoma-Kunz-80 dataset with the R2 database (R = 0.412, p = 1.0 × 10−4)." (PMID 38203530, 2023). "The PKHD1L1 expression was the highest in B cells and plasma cells in most datasets, suggesting that the PKHD1L1 expression is high in these infiltrated cells in melanoma and NSCLC." (PMID 38203530, 2023). "Therefore, we propose that the expression of PKHD1L1 in melanoma has a high prognostic value for predicting effective therapeutic outcomes." (PMID 38203530, 2023).
thyroid cancer (3 papers, 2021 to 2023). "The PKHD1L1 expression in thyroid cancer is downregulated compared to that in normal tissues." (PMID 38203530, 2023). "Similar to our results, a previous study reported that PKHD1L1 is underexpressed in thyroid cancer and may act as a tumor suppressor gene in the progression of thyroid cancer." (PMID 38203530, 2023). "Recently, PKHD1L1 was found to be a tumor suppressor associated with thyroid cancer cell progression; however, the clinical relevance of the PKHD1L1 expression in various types of cancers has not yet been studied." (PMID 38203530, 2023). "Next-generation gene sequencing showed that the polycystic kidney disease and liver disease like protein 1 (PKHD1L1) may be a tumor suppressor gene in thyroid cancer." (PMID 36118079, 2022).
bipolar disorder (1 paper, 2022). A disorder of the brain that causes unusual shifts in mood, energy, activity levels and the ability to carry out day-to-day tasks. "Pkhd1l1 has been associated with bipolar disorder in humans." (PMID 36712851, 2022).
cervical cancer (1 paper, 2022). A primary or metastatic malignant neoplasm involving the cervix. "In addition, our study firstly revealed the somatic mutations of KMT2D, NAV3 and PKHD1L1 in cervical cancer, to our knowledge." (PMID 36076209, 2022).
clear cell renal cell carcinoma (1 paper, 2024). "PKHD1L1 has been found to be significantly elevated in the urine of clear cell renal cell carcinoma patients." (PMID 39513726, 2024).
Hearing impairment (1 paper, 2024). A decreased magnitude of the sensory perception of sound. "Since the studied variants are also located in different residue positions in the PKHD1L1 protein sequence, the broad range of hearing impairment from these patients might suggest that these variants differentially impact the protein expression, folding, and/or the stability and function of PKHD1L1." (PMID 38459354, 2024). "However, in addition to hearing impairment, disruption of PKHD1L1 has also been associated with increased susceptibility to pentylenetetrazol-induced seizures in mice, indicating a possible role in maintenance of neuronal excitability in the central nervous system." (PMID 38459354, 2024).
hearing loss (1 paper, 2024). "Further research will be needed to determine the effect of age or noise trauma on the potential progression of PKHD1L1-linked hearing loss." (PMID 38459354, 2024). "Inclusion of PKHD1L1 as a hearing loss gene is supported by four families segregating plausible variants, in vitro functional data confirming their detrimental impact, as well as previously published mouse and zebrafish models demonstrating hearing loss." (PMID 38459354, 2024). "We sought to determine if biallelic variants in PKHD1L1 also cause hearing loss in humans." (PMID 38459354, 2024). "PKHD1L1 testing in individuals with mild–moderate hearing loss may identify further affected families." (PMID 38459354, 2024). "Interestingly, the PKHD1L1 gene has been suggested to be associated with adult‐onset hearing loss." (PMID 38459354, 2024).
Infertility (1 paper, 2024). "In contrast, the two recessive loci (near TBPL2 and PKHD1L1) were specifically associated only with infertility." (PMID 39566493, 2024).
lung carcinoma (1 paper, 2023). "Additionally, we performed a survival analysis in skin and lung cancer datasets using the PrognoScan database to investigate the prognostic implications of PKHD1L1 expression." (PMID 38203530, 2023).
pancreatic adenocarcinoma (1 paper, 2023). "Five cancer types, SKCM, pancreatic adenocarcinoma (PAAD), LUAD, liver hepatocellular carcinoma (LIHC), and stomach adenocarcinoma (STAD), showed significant correlations between the overall patient survival and PKHD1L1 mRNA expression (p < 0.01)." (PMID 38203530, 2023).
papillary thyroid cancer (1 paper, 2023). "Researchers found that PKHD1L1 might be a tumor suppressor gene associated with papillary thyroid cancer and might be a potential therapeutic target in the future." (PMID 37260987, 2023).
renal carcinoma (1 paper, 2023). A carcinoma arising from the epithelium of the renal parenchyma or the renal pelvis. "However, similar to ANGPTL6, the expression of PKHD1L1 in normal kidney tissues was higher than that in renal cancer tissues, and the high expression of PKHD1L1 also predicted a poor prognosis." (PMID 37260987, 2023).
cancer (11 papers, 2013 to 2025). A tumor composed of atypical neoplastic, often pleomorphic cells that invade other tissues. "Our investigation identified PKHD1L1 as the most frequently mutated Tdark gene across 28 types of cancer, indicating its potential as a broad therapeutic target." (PMID 38117798, 2023). "Notably, PKHD1L1 emerged as the most frequently mutated Tdark gene across all 28 cancer types, highlighting its potential significance in cancer development and progression." (PMID 38117798, 2023). "Here, the volcano plot analysis sheds light on some genes, including RGS5, BBOX1, PKHD1L1, and TXRND3, that are associated with cancer." (PMID 36790468, 2023). "We analyzed the differential expression patterns of PKHD1L1 in various cancer types using web-based gene expression analysis tools, such as GEPIA2 and the GENT2." (PMID 38203530, 2023). "Here, we systematically analyzed the clinical relevance of PKHD1L1 in the tumor microenvironment in multiple cancer types using various bioinformatic tools." (PMID 38203530, 2023). "This suggests that PKHD1L1 plays an important role in lymphocyte activation and provides crucial functions in the cellular immunity against cancer cells." (PMID 38203530, 2023). "GEPIA2 was used to identify the PKHD1L1 mRNA expressions in various cancers compared to normal tissues in RNA-sequencing data based on TCGA and GTEx datasets." (PMID 38203530, 2023). "Therefore, we systematically analyzed the expression of PKHD1L1 from publicly available cancer expression datasets and determined the relevance of the PKHD1L1 expression and patient survival rates in hot tumors." (PMID 38203530, 2023). "Notably, previous research has also indicated the substantial involvement of PKHD1L1 in cancer, underscoring its probable significance in the development and progression of this disease." (PMID 38117798, 2023). "The relationship between PKHD1L1 and cancer has been less reported." (PMID 37260987, 2023). "Collectively, we suggest that PKHD1L1 expressed in SKCM and LUAD could be associated with the infiltration of B cells and the activation of TIBs via BCR signaling, resulting in good prognoses in both types of cancer." (PMID 38203530, 2023). "Among the five cancer types, SKCM and LUAD showed the highest correlations and decreased PKHD1L1 expressions compared to their normal counterparts." (PMID 38203530, 2023). "The largest FMGS identified in all these cancer stages contained 8 genes (k = 8; RP1, PCDHAC2, TENM3, SPHKAP, ODZ3, ADAMTS18, SCN5A, PKHD1L1) found in SKCM-stage IV." (PMID 27556693, 2016). "Taken together, these results suggest that PKHD1L1 expression is highly correlated with the abundance of infiltrated B, CD8+ T, and NK cells, which may repress cancer progression in SKCM and LUAD." (PMID 38203530, 2023). "A positive correlation between patient survival and PKHD1L1 expression was also observed in cancer stages 1, 2, and 3 in SKCM and LUAD, but not in stage 4 in SKCM." (PMID 38203530, 2023). "Interestingly, amplification of PKHD1L1 and other genes at a similar distance from MYC but in the opposite direction from TONSL was observed in only 60% of MYC-amplified cancers." (PMID 37298484, 2023). "However, the role of the PKHD1L1 gene in various cancers has not yet been discussed." (PMID 38203530, 2023).
tumor (7 papers, 2021 to 2024). "Recent studies have reported an association between PKHD1L1 expression, tumor progression, and genetic modifications." (PMID 38203530, 2023). "Polycystic kidney and hepatic disease 1-like protein 1 (PKHD1L1) is a large transmembrane protein that is highly expressed in immune cells; however, its association with tumor progression remains unclear." (PMID 38203530, 2023). "Moreover, the association between the PKHD1L1 expression and OS in the clinicopathological parameters, including sex, age, and tumor stage, was analyzed in the SKCM-TCGA and LUAD-TCGA datasets using the R2 web tool." (PMID 38203530, 2023). "The Gene Expression Profiling Interactive Analysis 2 (GEPIA2) database and Gene Expression database of Normal and Tumor Tissues 2 (GENT2) were used to confirm the mRNA expression of PKHD1L1 in various types of tumors." (PMID 38203530, 2023). "In bulk profiles, we observed a decreased PKHD1L1 expression in tumor samples compared with that in normal thyroid tissues (TCGA cohort)." (PMID 34663816, 2021). "PKHD1L1 was lower in most tumor tissues than in normal tissues, and positively correlated with survival rates in SKCM and LUAD, suggesting that PKHD1L1 expression may be a favorable prognostic factor." (PMID 38203530, 2023). "CDCA7, CELSR3, PACS1, SNTB1, and TBC1D31 showed consistent upregulation in CRC tumor samples and pre-surgical cfRNA, while GFI1B, HPGD, SH3BGRL2, SIAE, PKHD1L1, and TDP2 showed downregulation in CRC tumor samples and pre-surgical cfRNA." (PMID 37091184, 2023). "We analyzed the correlation between the PKHD1L1 expression and the immune infiltration levels of B cells, CD8+ T cells, and NK cells after adjusting for the tumor purity." (PMID 38203530, 2023). "The Tumor Immune Estimation Resource (TIMER) and TISIDB were utilized to determine the potential correlation between the PKHD1L1 expression levels and TILs." (PMID 38203530, 2023). "In the HPA database, protein expressions of the seven genes (ADAMTS8, CCR2, CYSLTR2, FAM129C, FCER1A, GAPT, PKHD1L1, and ZNF831) were markedly low in tumor tissues with less intense antibody staining and fewer stained cells in LUAD." (PMID 36033829, 2022). "Collectively, our results suggest that PKHD1L1 can enhance the activity of other immune cells through B-cell activation by regulating BCR signaling, especially in SKCM and LUAD, resulting in a good prognosis via effective anti-tumor mechanisms." (PMID 38203530, 2023).
kidney (1 paper, 2024). "One such stereocilia protein, polycystic kidney and hepatic disease 1-like 1 (PKHD1L1), also called fibrocystin-L, is critical for hearing in mice." (PMID 38459354, 2024).
PKHD1L1 also shares sentences with these, for which no sentence is quoted: lung adenocarcinoma (3 papers); breast carcinoma (1); cervical squamous cell carcinoma (1); diffuse large B-cell lymphoma (1); endocervical adenocarcinoma (1); epithelioid mesotheliomas (1); esophageal carcinoma (1); lung squamous cell carcinoma (1); lymphoid neoplasm (1); Obesity (1); polycystic kidney and hepatic disease 1 (1); rectum adenocarcinoma (1); Respiratory tract infection (1); retinal degeneration (1); Sensory hearing loss (1); stomach adenocarcinoma (1); type 2 diabetes (1).